SMARCA4 (SWI/SNF related BAF chromatin remodeling complex subunit ATPase 4)
Diseases named in the same sentence as SMARCA4 in open-access papers (continued):
Sharing a sentence is not in itself a finding about the gene and the disease.
tumor (continued). "We evaluated the expression of SMARCA4 among the cancers of unknown primary and identified a significantly lower expression of SMARCA4 in tumours with biallelic LOF mutations compared to WT (p = 0.54 × 10−2)." (PMID 36883553, 2023). "SMARCA4 loss was global across all tumor components in 68% and heterogeneous in 14% of cases." (PMID 35307773, 2022). "This tumor is caused by an abnormality in SMARCA4/BRG1, which is involved in chromatin remodeling." (PMID 35151345, 2022). "Notably, we observed one case of a young patient in which a SMARCA4 frameshift mutation (p.Q306Rfs*12) was detected in tumor and in adjacent normal tissue, suggesting a germline or mosaic origin for this mutation." (PMID 36443295, 2022). "Thoracic SMARCA4‐deficient undifferentiated tumour (SMARCA4‐UT) is a high‐grade malignant neoplasm caused by the loss of function of SMARCA4, a key member of the SWItch/Sucrose‐NonFermentable (SWI/SNF) adenosine triphosphatase (ATPase)‐dependent chromatin remodelling complex." (PMID 35822082, 2022). "Thoracic SMARCA4-deficient undifferentiated tumors (SMARCA4-UT) are aggressive neoplasms." (PMID 35278076, 2022). "Computed tomography‐guided biopsy revealed a SMARCA4‐deficient undifferentiated tumor." (PMID 36523385, 2022). "Thus, PD-L1 expression cannot fully explain the observed sensitivity of SMARCA4-deficient tumours to anti-PD-1 blockade." (PMID 35327375, 2022). "Remarkably, there seems to be a striking organ-specific clustering of mutations in certain SWI/SNF genes, so that ARID1A mutations prevail in genital tract malignancies while SMARCB1 and SMARCA4 mutations predominate among SWI/SNF-driven neoplasms of soft tissue and lung, respectively." (PMID 35307773, 2022). "Studies have also revealed that SMARCA4 expression was associated with poor prognosis of multiple cancer types, including liver hepatocellular carcinoma and kidney renal clear cell carcinoma, challenging the role of SMARCA4 as a tumor suppressor." (PMID 34675941, 2021). "As the poor prognosis is recognized in SMARCA4-deficient tumors, the presence of frequent co-mutation with other tumor suppressor genes, such as STK11 and/or KEAP1, further dampens the regrettable overall survival and shortens the progression free survival outcome of the disease." (PMID 34440689, 2021). "Furthermore, we observed >50% residual tumor (TRG3) in the two cases with SMARCA4 deficiency and preoperative CTx." (PMID 34359794, 2021). "In the present study, through data mining analyses, we visualized the prognostic landscape of SMARCA4 expression and mutation across cancers and analyzed the expression of the SMARCA4 gene and its association with tumor-infiltrating immune cells (TIICs) and related immune markers." (PMID 34675941, 2021). "As EPHA5 is known to be significantly upregulated in SCCOHT as well, Ephrin signaling might be one of the tumor-promoting pathways in tumors driven by SMARCA4 deficiency." (PMID 33331994, 2021). "This hypothesis may explain the diverse morphology patterns that are observed in the SMARCA4-dNSCLCs; however, the exact mechanism of the tumor development and EMT with dual loss of BRG1 and BRM as the causative factors is unknown." (PMID 34440689, 2021). "Notably, tumor cells showed a heterogeneous loss of SMARCA4 expression pattern and intact SMARCB1 expression." (PMID 33836796, 2021). "For example, tumors with rhabdoid features are aggressive and of high grade due to the dedifferentiation from a normal cell or low-grade tumor, induced by dual deficiency in SMARCA4 and SMARCA2, but an effective therapy to improve the outcome is still being investigated." (PMID 34440689, 2021). "This suggests that altered Ca2+ homeostasis may also directly contribute to the tumorigenesis of SMARCA4/2 loss through suppression of apoptosis, as previously shown for other major tumor suppressors PTEN, BAP1, and PML66–68." (PMID 34518526, 2021).
tumor (continued). "Interestingly, SMARCA4 acts primarily as a tumor suppressor, as its loss leads to inactivation of the Rb pathway in ovarian and non-small-cell lung cancers, but is also considered an oncogene in other contexts." (PMID 33513764, 2021). "In addition, focal loss of SMARCA4 was observed in undifferentiated areas of one additional tumor, with retained expression in the glandular areas." (PMID 33435234, 2021). "Moreover, the tumor tissue overexpressed SOX2, a characteristic finding of SMARCA4-deficient neoplasms." (PMID 34131151, 2021). "Firstly, reintroducing SMARCA4 into SMARCA4‐deficient tumour cells resulted in Rb‐dependent cell cycle arrest and a flattened morphology, suggesting that SMARCA4 may function as a tumour suppressor gene." (PMID 32162380, 2020). "The tumour was diagnosed as a SMARCA4-deficient thoracic sarcoma." (PMID 32884816, 2020). "This evidence supports the notion that the putative tumour suppressor function associated with SMARCA4 loss‐of‐function mutations in human and mouse neoplasms is tissue and cell type‐dependent and further does not predispose cells of the mature T‐cell lineage to oncogenic transformation." (PMID 32162380, 2020). "Therefore, the association between the presence of SMARCA4 mutations, a high tumor mutation burden, and the efficacy of ICIs for PC of the lung is still unclear." (PMID 32578376, 2020). "Higher tumor mutation burden (TMB) was found in the SMARCA4 variant population in all tumor types." (PMID 33144586, 2020). "Parallel evolution of five subclonal SMARCA4 mutations in this tumour with truncal ARID1A mutations suggests that SWI/SNF-complex aberrations are not only important for carcinogenesis but that progressive inactivation may contribute to cancer progression." (PMID 31949146, 2020). "Assessing heterogeneous driver mutations revealed striking examples of parallel evolution, a strong signal that these evolved through Darwinian selection:7,17,34,35 Tumour 2 acquired five subclonal mutations in SMARCA4, encoding a catalytic subunit of the SWI/SNF-complex." (PMID 31949146, 2020). "In contrast, the function of SMARCA4 in cancer has also been linked to a tumor suppressive role." (PMID 31406271, 2019). "Both SMARCA2 and SMARCA4 are tumor suppressors and mutations are frequently found in cancers, which may suggest an additional link between FANCA mutations and cancer predisposition." (PMID 31461451, 2019). "Furthermore, we find that high levels of SMARCA4 expression are associated with an advanced tumor stage and histological grade in LIHC, and with increased metastasis in KIRC." (PMID 29391527, 2018). "Interestingly, at the level of gynecologic tumors, SMARCA4 loss was also observed in poorly differentiated endometrioid adenocarcinoma of the uterus, a rhabdoid variant of this tumor." (PMID 29389895, 2018). "Mutations in SMARCA4 in tumours are reported less frequently than in cell lines." (PMID 28102363, 2017). "The tumours of both patients displayed loss of the SMARCA4 protein by immunohistochemistry." (PMID 27866340, 2017). "We detected a de novo germline heterozygous nonsense mutation in exon 19 of SMARCA4 (c.2935C > T;p.Arg979*), and a somatic frameshift mutation in exon 6 (c.1236_1236delC;p.Gln413Argfs*88), causing complete loss of SMARCA4 immunostaining in the tumour." (PMID 28608987, 2017). "The similarity between SCCOHT and rhabdoid tumours should be recognized, as infant carriers of SMARCA4 mutations may be at risk for these tumours in addition to SCCOHT." (PMID 27866340, 2017). "However, the oldest woman to date diagnosed definitively with SCCOHT (showing loss of SMARCA4 staining in her tumour) was 56 years old at diagnosis." (PMID 27866340, 2017). "The precise contributions of SMARCA4 loss to tumour initiation and/or progression are largely unknown." (PMID 28102363, 2017).
tumor (continued). "Moreover, SCCOHT-1 tumor cells are carrying a defective SMARCA4 gene with a loss of BRG1 protein expression and likewise, BIN-67 cells demonstrated biallelic deleterious SMARCA4 gene mutations which confirms the results in SCCOHT patient biopsies." (PMID 26436697, 2015). "Researchers believe SMARCA4 loss may disrupt normal cellular processes, leading to altered gene expression patterns and dysregulation of pathways involved in cell growth, differentiation, DNA repair, and tumor formation." (PMID 41577374, 2026). "In addition, somatic (tumor) testing can help clarify the nature of SMARCA4 variants." (PMID 40896427, 2025). "Given these implications, germline SMARCA4 testing and cascade screening of at-risk relatives are essential to enable tailored surveillance strategies, including periodic imaging and biochemical assessments for early tumor detection and improved clinical outcomes." (PMID 41312169, 2025). "Since SMARCA4 is generally regarded as a tumor suppressor gene and SMARCA4 mutations are thought to be involved in cancer progression, SMARCA2 targeting and the induction of cell death using the concept of synthetic lethality may be considered in the treatment of SMARCA4-mutated cancers." (PMID 38610978, 2024). "EBVaGC received significant benefit from the suggested ICI combined with CTLA-4 blockade over single immunotherapy, suggesting that tumor mutational burden and SMARCA4 mutations may be useful biomarkers for the prediction of ICI efficacy in patients with EBVaGC." (PMID 37000076, 2023). "In addition to these molecular differences, the most striking immunohistochemical differences between solid and glandular areas were the complete loss of SMARCA4 in the solid component in one tumor and the focal loss of ARID1A in the undifferentiated area of two tumors." (PMID 33435234, 2021). "Notably, tumor cells showed loss of SMARCA4 protein and intact SMARCB1 protein expression." (PMID 33836796, 2021). "Furthermore, the similarity between SCCOHT and RTs is striking and, in addition to SCCOHT, infant SMARCA4 mutation carriers may be at risk for these tumours." (PMID 27866340, 2017). "Integrative multi-omics analyses revealed that SMARCA4 directly cooperates with FOSL1 at active enhancers, leading to the activation of tumor-associated transcriptional programs." (PMID 42010258, 2026). "SMARCA4 mutations, similar to KRAS mutations, are often smoking-associated and linked to high tumor mutation burden." (PMID 41541668, 2026). "At this stage, we know little about the dual role of SMARCA4 as both a tumor suppressor and context-dependent oncogene in KRAS-driven cancers." (PMID 41541668, 2026). "Both in vitro and in vivo experimental results demonstrated that inhibiting SMARCA4 effectively suppresses tumor progression and reverses neuroendocrine transformation." (PMID 41881959, 2026). "Functionally, genetic depletion of FOSL1 or pharmacological inhibition of SMARCA4 reduced cell proliferation and migration and suppressed tumor growth in vitro and in vivo." (PMID 42010258, 2026). "Given the inherent commonality of their biology (i.e. biallelic inactivation of SMARCB1 or more rarely SMARCA4) the therapeutic approach should be similar for intra-cranial and extra-cranial tumours." (PMID 41680284, 2026). "Molecular profiling revealed 90% PD-L1 expression, multiple oncogenic mutations including SMARCA4 and POLE, and a mutational signature consistent with high tumor mutational burden (TMB), suggesting potential immunogenicity." (PMID 41768232, 2026). "These structural domains likely play a pivotal role in the tumor‐suppressive function of SMARCA4, with postmutation effects significantly impacting patient prognosis." (PMID 41577374, 2026).
tumor (continued). "These structural domains likely play a pivotal role in the tumor‐suppressive function of SMARCA4 and significantly impact the prognosis of NSCLC with post‐mutation." (PMID 41577374, 2026). "A947 is another potent, moderately selective SMARCA2 degrader, which achieves approximately 28‐fold preferential degradation of SMARCA2 with minimal growth inhibition in SMARCA4‐wild‐type tumours." (PMID 41537447, 2026). "In PTEN-deficient cells, BRG1 (SMARCA4) regulates c-Myc and MAPK signaling, and stabilization of BRG1 maintains tumor cell growth." (PMID 41294748, 2025). "In vivo studies using the Ras-transgenic mouse model of HCC demonstrated that silencing GAS5 or SMARCA4 or overexpressing miR-423-3p significantly reduced tumor development." (PMID 40451925, 2025). "A genomic next-generation sequencing study in renal cell carcinoma BMs found an enrichment of the SMARCA4 gene in BM tumors in contrast with primary tumor and extracranial lesions." (PMID 40076927, 2025). "Knockdown of GAS5 (si-GAS5), SMARCA4 (si-SMARCA4) or overexpression of miR-423-3p mimics significantly inhibited tumor cell growth and proliferation rates to similar degrees in Hep3B, Huh7 and SNU-449 cell lines." (PMID 40451925, 2025). "Recent clinical research identified SMARCA4 as a tumor suppressor gene, which typically exhibits a small cell/rhabdoid morphology, often accompanied by BRG1 loss." (PMID 41142791, 2025). "A detailed analysis showed that the si-Gas5 + si-Smarca4 mix inhibited tumor growth more effectively than either si-Gas5 or si-Smarca4 alone." (PMID 40451925, 2025). "Thoracic SMARCA4-UT is an uncommon yet aggressive neoplasm that predominantly afflicts heavy male smokers." (PMID 41261718, 2025). "In this case, we described a malignant tumor formed in the uterus occurring in a SMARCA4 deletion type and discussed its clinical characteristics, differential diagnosis, treatment and related literature analysis." (PMID 40826772, 2025). "Histologically, SMARCA4-UT is characterized as a poorly differentiated tumor exhibiting rhabdoid or epithelioid features." (PMID 41142791, 2025). "MRTK is a highly aggressive tumor seen in the context of RTPS, generally in RTPS type 1 (SMARCB1/INI1 mutations) and rarely in RTPS type 2 (SMARCA4 mutations)." (PMID 39847050, 2025). "CK, Vimentin and Ki-67 (>75%) were positive in the tumor cells, whereas SMARCA4, CD20, LCA, CD3, HMB-45, Melan-A, Epstein-Barr virus (EBV) were negative." (PMID 41170461, 2025). "When diagnosing some of these uncommon neoplasms, the pathologist should raise the possibility of a germline mutation, for example DICER1 in SLCT or SMARCA4 in SCCOHT and recommend genetic referral and germline testing." (PMID 40739655, 2025). "SMARCA4-UT is classified as an undifferentiated tumor, whereas SMARCA4-dNSCLC represents a subtype of NSCLC." (PMID 41142791, 2025). "SMARCA4 expression was diffusely lost in the A549 xenograft tumor but retained in the other three cell lines (the bottom row)." (PMID 38710944, 2025). "miR-423-3p normally functions as a tumor suppressor by targeting SMARCA4, an oncogene involved in chromatin remodeling and transcriptional regulation." (PMID 40451925, 2025). "In four patients, longitudinal analyses of subsequent lesions showed the maintenance of most genomic alterations and enrichment in missense or splice variants in PMS2, SMARCA4, ARID1A, AKT1, BMPR1A, and PTEN, indicating the occurrence of tumor evolution." (PMID 41514647, 2025).
tumor (continued). "The report provides novel insights into the distinct roles of SMARCA2 and SMARCA4 in LUAD pathogenesis, highlighting the immunosuppressive tumor microenvironment associated with SMARCA2 deficiency." (PMID 40453096, 2025). "ATRT is an aggressive tumor mainly affecting infants, but with rare adult cases linked to inactivation of SMARCB1 (INI1) or SMARCA4 (BRG1)." (PMID 40851939, 2025). "The SMARCA4 gene encodes the BRG-1 protein, which is a subunit of the SWI/SNF chromatin remodeling complex and functions as a tumor suppressor." (PMID 40826772, 2025). "Among its core components, SMARCA4 (SWI/SNF-related, matrix-associated, actin-dependent regulator of chromatin, subfamily A, member 4; also known as BRG1) functions as a tumor suppressor and is frequently altered in multiple malignancies." (PMID 40867304, 2025). "Immunostaining of GLTSCR1, a nucleating member of ncBAF complexes, was significantly elevated in de-differentiated tumor compartments, with similar intensities of the ATPase subunit, SMARCA4, across both UD and WD compartments." (PMID 41279405, 2025). "ATRT is an aggressive tumor primarily affecting infants, with rare adult cases linked to inactivation of SMARCB1 (INI1) or SMARCA4 (BRG1)." (PMID 40851939, 2025). "In 2022, a study conducted at the University Hospital of Strasbourg in France examined the immune desert characteristics of the tumor microenvironment (TME) in SMARCA4-UT patients by analyzing the infiltration levels of immune cells." (PMID 41142791, 2025). "SMARCA4-UT is a high-grade tumor that occurs in adults with a wide age range and shows a striking male predominance." (PMID 40406754, 2025). "Combined with IHC results, it was considered to be SMARCA4-dNSCLC, and PD-L1 staining revealed a tumor proportion score (TPS) of 8%." (PMID 40313929, 2025). "ATRT is a rare, aggressive neoplasm predominantly affecting young children and is typically associated with inactivating mutations in the SMARCB1 or SMARCA4 tumor suppressor genes." (PMID 41155355, 2025). "The deficiency of SMARCA4 impairs the function of the SWI/SNF complex, compromising chromatin regulation and increasing susceptibility to malignant transformation and tumor progression." (PMID 40416876, 2025). "Loss of SMARCA4 function disrupts NEUROD1 expression, leading to changes in tumor differentiation and resistance to therapy." (PMID 40333678, 2025). "In conclusion, SMARCA4-UT is a rare, high-grade malignancy that often presents without distinct clinical, radiologic, or pathologic features, making the diagnosis of this tumor a challenge." (PMID 40406754, 2025). "While cisplatin treatment alone significantly reduced tumor size, combination with the SMARCA4 targeting PROTAC AU-15330 resulted in a higher percentage of mice with reduced tumor size, reduced tumor proliferation, and increased immune infiltration." (PMID 39813356, 2025). "In four patients, longitudinal analysis of subsequent lesions highlighted an increase in mutations, like missense or splice variants in the PMS2, SMARCA4, ARID1A, AKT1, BMPR1A, and PTEN genes, suggesting tumor evolution." (PMID 41514647, 2025). "Upregulated immunomodulators in HTE tumours included SLAMF7, associated with the presence of SMARCA4 mutations and a target of the monoclonal antibody elotuzumab." (PMID 40849356, 2025). "BRG1, encoded by the SMARCA4 gene, has been reported to function both as a tumor suppressor and as an oncogene." (PMID 41514577, 2025). "OXPHOS was increased in tumors with SMARCA4 mutation and OXPHOS inhibitor (IACS-010759) represses OXPHOS, thereby inducing tumor cell death and inhibiting tumor growth." (PMID 38347129, 2024). "SMARCA4’s histology is characterized by epithelioid and rhabdoid tumor cells with poorly defined nuclear borders and prominent nucleoli." (PMID 38542211, 2024). "The next-generation sequencing (NGS) of case 1 confirmed deletion mutations in SMARCA4, RAD51 and TSC2, and the tumor mutation burden (TMB) was 0.96 mutations/Mb." (PMID 38877473, 2024).